CNIH1 (cornichon family member 1)
Description:
Involved in the selective transport and maturation of TGF-alpha family proteins.
Synonyms: CNIH-1; TGAM77; CNIH; CNIL
Tractability: Antibody: UniProt predicts a signal peptide or a membrane-spanning region.
Gene: Protein-coding gene on chromosome 14 (54,423,561 to 54,441,439, reverse strand). Ensembl gene ENSG00000100528.
Subcellular location: Endoplasmic reticulum membrane; Golgi apparatus membrane
Subcellular location (Human Protein Atlas): Vesicles
Pathways (Reactome):
Vesicle-mediated transport: COPII-mediated vesicle transport; Cargo concentration in the ER
Gene Ontology:
Molecular function: protein binding; signaling receptor binding
Biological process: immune response; signal transduction; vesicle-mediated transport
Cellular component: endoplasmic reticulum membrane; endoplasmic reticulum-Golgi intermediate compartment membrane; ER to Golgi transport vesicle membrane; Golgi membrane
Genetic constraint (gnomAD): Loss-of-function variants: 5 observed, 9.32 expected, observed/expected ratio (o/e) 0.54, 90% interval 0.28 to 1.13. That is too few expected variants to judge how well the gene tolerates losing a copy. Missense variants: 92 observed, 98.49 expected, observed/expected ratio (o/e) 0.93, 90% interval 0.79 to 1.11. Synonymous variants: 41 observed, 34.36 expected, observed/expected ratio (o/e) 1.19, 90% interval 0.93 to 1.55.
Homologues: Orthologues: chimpanzee CNIH1 (100% identical), dog CNIH1 (100% identical), guinea pig CNIH1 (100% identical), macaque CNIH1 (100% identical), mouse Cnih1 (100% identical), tropical clawed frog cnih1 (99% identical), rat Cnih1 (97% identical), pig CNIH1 (94% identical), rabbit CNIH1 (79% identical), Drosophila melanogaster cni (67% identical), Caenorhabditis elegans cni-1 (59% identical). Paralogues in human: CNIH3 (75% identical), CNIH2 (72% identical), CNIH4 (36% identical), PPCS (22% identical).
Diseases named in the same sentence as CNIH1 in open-access papers:
CNIH1 is named in the same sentence as 5 diseases in open-access papers, as found by Europe PMC text mining. Sharing a sentence is not in itself a finding about the gene and the disease. The quoted sentences say what the papers report.
tumor (1 paper, 2022). "Since GRIA1 was downregulated in LUAD tumor tissues, CNIH1 and AP3S1 were selected for further studies." (PMID 36524130, 2022). "Apart from GRIA1, upregulated mRNA levels of CNIH1, KIF20A, GALNT2, and AP3S1 were observed in tumor tissues in these datasets." (PMID 36524130, 2022). "In the TCGA dataset, mRNA levels of four genes (CNIH1, KIF20A, GALNT2, and AP3S1) were highly expressed in tumor tissues, while GRIA1 levels were downregulated in tumor tissues." (PMID 36524130, 2022). "The mRNA levels of CNIH1 and AP3S1 detected in our own LUAD samples were not fit the public data, which may result from that expression of these genes in different tumor stages of LUAD maybe different." (PMID 36524130, 2022).
CNIH1 also shares sentences with these, for which no sentence is quoted: cancer (2 papers); dental caries (1); hereditary spastic paraplegia (1); schizophrenia (1).